SLFN5 (schlafen family member 5)
Diseases named in the same sentence as SLFN5 in open-access papers (continued):
Sharing a sentence is not in itself a finding about the gene and the disease.
tumor (continued). "Although its effects vary across different tumor types, an increasing body of research suggests that SLFN5 may serve as a crucial target for cancer treatment." (PMID 37771431, 2023). "In particular, the molecular mechanism of human SLFN5 in tumor control is not well understood." (PMID 35037067, 2022). "However, high SLFN5 expression in glioblastoma, pancreatic ductal carcinoma, and prostate cancer can promote tumor proliferation, invasion, and metastasis." (PMID 36090985, 2022). "Depending on the tumor type, SLFN5 can have inhibitory or stimulatory effects on tumorigenesis." (PMID 35037067, 2022). "This suggests a potential role of SLFN5 in the anti-tumor effects of IFN-α in humans." (PMID 34571887, 2021). "Consequently, SLFN5 may serve as a potential therapeutic target for cancer treatment, with treatment strategies targeting SLFN5 aimed at inhibiting tumor cell proliferation and transformation." (PMID 37771431, 2023). "Thus, future therapeutic targeting of SLFN5 in malignancies may require precise analysis of other associated factors, and the design of therapeutic targeting of a particular tumor may be required for the selective targeting of SLFN5." (PMID 35216035, 2022). "Moreover, SLFN5 RNA expression in tumour tissues decreased with metastasis (P = 0.008)." (PMID 32488136, 2020). "Blocking expression of Slfn5 in PDAC enhanced IFN responses, suppressed tumor growth, and prolonged survival in immunocompetent mice." (PMID 41591829, 2026). "The results showed that the high SLFN5, SLFN11, SLFN12, SLFN12L, and SLFN13 expression in GC was positively correlated with lymph node metastasis, tumor stage, and tumor grade." (PMID 36090985, 2022). "Expression of both the long SLFN5, which targets to the nucleus, and the intermediate SLFN12, which targets to the cytosol, is correlated with survival, tumor growth, and metastasis in triple negative breast cancer." (PMID 34571887, 2021). "Mouse SLFN1, SLFN2, SLFN3 and SLFN5 were all shown as proliferation suppressors when individually expressed in NIH3T3 murine fibroblasts, T cells or various human tumour cells." (PMID 29563550, 2018). "The results demonstrated that SLFN5, SLFN11, SLFN12, SLFN12L, and SLFN13 expression in tumor tissues was significantly higher than that in normal tissues in paired, and unpaired tests, implying that they may play a role in promoting tumor progression in GC." (PMID 36090985, 2022). "The SLFN5 expression exhibits a negative correlation with tumor progression in human BRCA." (PMID 39558948, 2024).
cancer (13 papers, 2020 to 2024). A tumor composed of atypical neoplastic, often pleomorphic cells that invade other tissues. "Herein, we comprehensively examined SLFN5 expression patterns across diverse cancer types to ascertain commonalities and distinctions in its expression profile." (PMID 39310264, 2024). "In summary, SLFN5 can both promote or inhibit the ability of cancer cells to migrate and invade in a cell/tissue-dependent manner." (PMID 38791884, 2024). "SLFN5 plays different roles in specific types of cancer cells through distinct mechanisms, exhibiting inhibitory effects in some cancers while promoting effects in others." (PMID 37771431, 2023). "Future studies should continue to investigate the mechanisms and regulatory pathways of SLFN5 in tumors, aiming to provide more effective approaches and strategies for cancer prevention and treatment." (PMID 37771431, 2023). "Studies have shown that human SLFN5 (SLFN5) plays a regulatory role in the proliferation of several specific cancer cells." (PMID 37771431, 2023). "In conclusion, as a member of the Schlafen family, SLFN5 plays an important role in malignant tumors." (PMID 37771431, 2023). "SLFN5 downregulates membrane type 1 matrix metalloproteinase (MT1-MMP) expression through the AKT/GSK-3β/β-catenin pathway in several types of cancer cells, exerting inhibitory effects on migration and invasion." (PMID 37771431, 2023). "GSK-3β-regulated MMP expression, for example, was involved in SLFN5-controlled inhibition of cancer cell migration and invasion." (PMID 35095838, 2021). "However, whether SLFN5 is implicated in other steps in cancer metastasis is unknown." (PMID 32488136, 2020). "Our present findings showed that SLFN5 can maintain or restore epithelial morphology, and inhibit the invasion and metastasis of cancer cells." (PMID 32488136, 2020). "Therefore, further research on the mechanisms of SLFN5 in different types of malignant tumors is of significant importance." (PMID 37771431, 2023). "SLFN5, as a transcriptional repressor, plays a crucial role in various cancers." (PMID 37771431, 2023). "Thus, SLFN5 suppresses cancer cell proliferation and induces apoptosis by regulating the ZEB1/PTEN/AKT pathway and purine metabolism." (PMID 37771431, 2023). "Our previous study revealed that high or low expression levels of SLFN5 lead to epithelial or interstitial morphology in some cancer cells, which indicates that SLFN5 may exert an important function on cellular EMT and invasion." (PMID 36033389, 2022). "SLFN5 expression has been correlated with cancer progression." (PMID 35768579, 2022). "Together, our findings suggest that SLFN5 plays inhibitory roles in cancer cell metastasis." (PMID 32488136, 2020). "Work from our group has provided evidence that SLFN5 is important for the tumorigenesis of pancreatic ductal adenocarcinoma (PDAC), an aggressive cancer with poor outcomes." (PMID 38791884, 2024). "SLFN11, SLFN5, SLFN13, and SLFN12 exhibit a wide range of transcription levels in cancer cells, whereas SLFN12L, SLFN14 and SLFNL1 are barely expressed in cancer cell lines." (PMID 35768579, 2022). "It has been found recently that human SLFN5 can inhibit ZEB1 transcription by directly binding to the SLFN5 binding motif on the ZEB1 promoter, thereby maintaining the epithelial cell morphology and inhibiting metastasis in BRCA mutant cancer cells." (PMID 35216035, 2022). "The SLFN5 and SLFN13 expressions in GC may play a significant role in cancer promotion and can be utilized to predict the GC prognosis." (PMID 36090985, 2022). "As a transcriptional repressor, SLFN5 prevents epithelial-mesenchymal transition (EMT) in breast cancer and targets the ZEB1 promoter to abrogate ZEB1 transcription and the downstream PTEN/AKT/cyclin D1 signaling cascade, ultimately prompting cancer cell death." (PMID 35768579, 2022).
infection (4 papers, 2022 to 2026). The state of being infected such as from the introduction of a foreign agent such as serum, vaccine, antigenic substance or organism. "Infection at increasing MOIs revealed a clear dose-dependent increase in SLFN5 expression, demonstrating that the extent of APA remodeling correlates with viral input." (PMID 41405390, 2026). "To further examine the relevance of these infection-induced changes, we measured SLFN5 expression, a readout of APA regulation, under different experimental conditions." (PMID 41405390, 2026). "Moreover, time-course experiments showed that SLFN5 expression increased progressively with infection time, consistent with a temporal window during which capsid–CPSF6 interactions are active in the nucleus." (PMID 41405390, 2026). "Interestingly, we observed that the effect on SLFN5 expression was dependent on the duration of infection, with the greatest increase in SLFN5 levels occurring at 96 h post-infection." (PMID 41405390, 2026). "First, SLFN5 is an interferon-stimulated gene and upregulated in response to infection by IAV41." (PMID 40759647, 2025). "Then, as viral replication and innate immune signaling proceed during infection with ICP0 RF, by 8 hpi, the interaction profile of SLFN5 remains correlated with IFI16, while those of PML, DAXX, and SP100 diverge to cluster with one another." (PMID 40577456, 2025). "Immediately upon infection, the majority of HSV-1 DNA is surrounded by PML protein; however, when ICP0 is expressed, PML is rapidly eliminated, and viral DNA is once again entrapped by SLFN5 protein." (PMID 35216035, 2022). "The observation that SLFN5 regulates immune responses, and is also targeted by ICP0, suggests that it may form part of a ‘self-guarded’ immune pathway to monitor infection." (PMID 35216035, 2022). "Within the first 24 h after infection, SLFN5 depletion promotes the expression of viral immediate-early and early gene transcripts; however, this is reversed in the late phase, resulting in the reduced expression of these viral genes in the absence of SLFN5." (PMID 35216035, 2022).
adenocarcinoma (1 paper, 2021). A common cancer characterized by the presence of malignant glandular cells. "In vitro, SLFN5 knockdown in A549 adenocarcinoma human alveolar basal epithelial cells upregulates metalloproteinases, specifically matrix metalloproteinase MMP9." (PMID 34571887, 2021).
SLFN5 also shares sentences with these, for which no sentence is quoted: hepatocellular carcinoma (2 papers); atrophic gastritis (1); bacterial infection (1); breast tumor (1); colorectal cancer (1); dementia (1); diabetes (1); gastric tumor (1); influenza (1); metabolic syndrome X (1); renal clear cell carcinoma (1); renal papillary cell carcinoma (1); type 2 diabetes (1).